CD24 (CD24 molecule)
Diseases named in the same sentence as CD24 in open-access papers (continued):
Sharing a sentence is not in itself a finding about the gene and the disease.
tumor (continued). "Preclinical studies with anti-CD24 antibody treatment has impeded tumor growth in hepatocellular carcinoma 151, colorectal and pancreatic adenocarcinoma 152, and reduced CSC populations." (PMID 32194856, 2020). "Another tumor-related mechanism of CD24 is the connection between CD24 and signal factors in the lipid rafts microdomains, such as Src kinase." (PMID 32765491, 2020). "CD24 meets the criteria of a good imaging biomarker, as it is almost uniquely expressed on tumor cells and predominantly physiologically expressed on developing hematological cells, with low expression in healthy tissues." (PMID 33260974, 2020). "Pretreatment BCSC markers (CD44 and CD24) were assessed by immunohistochemistry on formalin-fixed paraffin-embedded tumor tissues from a primary or metastatic site." (PMID 32684928, 2020). "It is known that migration of the breast CSC population (CD44+ CD24-/low) gradually increases with tumor stage progression and that PKCλ KD decreases the migration potential of multiple TNBC cell lines." (PMID 32658903, 2020). "FIGS enabled the intraoperative identification of the primary tumor and miniscule metastases in seven heterogeneous CD24-expressing PDX models, and ultimately improved tumor resection in preclinical orthotopic PDX." (PMID 33260974, 2020). "CD24 on the surface of tumor cells can also be regulated by other factors to promote tumor immune escape." (PMID 32765491, 2020). "CD24 expression in HCC has also been associated with iNOS-induced TACE/ADAM17-dependent activation of Notch1, which is linked to tumor progression and stemness." (PMID 32183251, 2020). "CD24 has been investigated for use in molecular targeted therapy, highlighting the potent anti-tumor effect of CD24 blockade and the potential to unravel the blockade of the immune system, suggesting the potential of its use beyond FIGS." (PMID 33260974, 2020). "First, CD24 is an alternative ligand of P-selectin, an adhesion receptor expressed on activated endothelial cells and platelets, promoting metastatic potential through binding CD24+ tumor cells." (PMID 33260974, 2020). "Again, all dormant tumor cells that grew in culture from the lungs showed comparable levels of expression of neu or EpCAM and were predominated by the CD24+CD44+ fraction." (PMID 33115528, 2020). "Most scholars believe that CD44 + CD24-/low cells represent interstitial breast CSCs, which are mainly distributed in the edge of tumor invasion." (PMID 33282946, 2020). "Third, cancer stem cells (CSCs), a continuously proliferating subset of cancer cells with stem-like and tumor cell characteristics, express, among other markers, CD24, CD44, and CD133, and they increase tumorigenic potential and drive growth and metastasis." (PMID 33260974, 2020). "Recently, preclinical studies have demonstrated the benefit of CD24-targeted contrast agents for non-invasive fluorescence imaging, as well as improved tumor resection by employing CD24-targeted FIGS in orthotopic patient-derived xenograft models of EOC." (PMID 33260974, 2020). "Current studies suggest that HIF-1α can induce the expression of CD24 at the transcriptional level, which further points out the importance of hypoxia and the expression of CD24 for tumor immune escape." (PMID 32765491, 2020). "AC009 also reduced cancer stem-cell marker CD44+/CD24+ expression and restored the tumor inhibition effect of cetuximab in KRAS-mutant CRC." (PMID 31717759, 2019). "In order to study the effect of MSCs on Tumor Cell marker flow cytometry analysis were performed on CD24 and CD44." (PMID 31351482, 2019). "Subcutaneous injections of 1x106 CD24+ and CD24- purified cell populations recapitulated tumour formation in vivo, with resulting tumours appearing as a highly vascularised tumour mass of nucleated cells." (PMID 30657775, 2019). "After 14 days of treatment, CUR-loaded CSO-SA micelles also caused a reduction in tumor size and the subpopulation of CD44+/CD24+ cell in nude mice tumor tissue." (PMID 30890933, 2019).
tumor (continued). "The minimum biomarkers for BCSCs are the cell-surface markers CD44+/CD24- and CD44 upregulation is linked to tumor formation." (PMID 31480284, 2019). "In vivo transplantation of FACS sorted 4x105 CD24+/CD15+ cells recapitulated tumour formation in 5/10 cases (95.2+/-31.86 days)." (PMID 30657775, 2019). "Remarkably, the CD24-CAR-NK-92 cells completely eradicated SKOV3 and OVCAR3 tumor cells, which highly express CD24." (PMID 30717444, 2019). "CD24-/CD15+ expression was predominantly found on WNT tumours, while CD24+/CD15- expression was correlated with SHH, Group 3 or Group 4 designation." (PMID 30657775, 2019). "Recently, tumor cells that expressed CD24 will inhibit phagocytosis by macrophages through binding Siglec-G in-trans manner, which also indicates that different substrate recognition patterns of Siglec-G." (PMID 31781099, 2019). "We found that ALDH+ cells are mainly localized in the tumor interior, whereas CD44+/CD24− cells are enriched at the tumor’s invasive edge." (PMID 30659204, 2019). "In mice bearing subcutaneous human PDAC cell line Capan-1 (positive for both HER2 and CD24), intratumor injection of the CAR T cells targeting either HER2 or CD24 greatly inhibited tumor growth, in some cases, eradicated tumors." (PMID 30809507, 2019). "Blockade of CD24-Siglec10 enhances clearance of CD24+ tumours and is a potrntial immunotherapy target." (PMID 31614918, 2019). "Blockage of CD24 by a monoclonal antibody reduced tumor growth in vivo, suggesting that inhibition of this “don't eat-me” signal suffices to enable phagocytosis of live cancer cells." (PMID 31998312, 2019). "CUR-loaded CSO-SA micelles reduced the size of tumor and the subpopulation of CD44+/CD24+ cell in nude mice tumor tissue." (PMID 30890933, 2019). "The adoptive transfer of HER2-CAR or CD24-CAR to mice bearing these xenografts significantly arrested the tumor growth, but to a different degree, dependent on the CAR-targeted antigen specificity." (PMID 30809507, 2019). "CD24-/CD15+ transplantations resulted in 1 tumour following 7 transplantations (day 42), while CD24-/CD15- gave rise to 1 tumour following 10 transplantations (day 61), indicating a rare capability of these populations to initiate tumorigenesis." (PMID 30657775, 2019). "We reported CD24 amplification in carcinoma of breast, ovarian, lung but not in the prostate, and the copy number amplification was strongly correlated with CD24 mRNA overexpression, which in turn correlated with signature genes of tumor growth and metastasis." (PMID 31244889, 2019). "The CD24+ cancer cells were found not only in the peripheral tumor tissues but also on the solid tumor." (PMID 30728024, 2019). "Many researchers have found that cells induced to undergo EMT can gain cancer stem cell (CSC) properties, with the enrichment of a CD44(+)/CD24(−) subpopulation, which is responsible for tumour initiation and formation." (PMID 31684910, 2019). "PSI-697 also significantly reduced the number and size of tumor spheroids, implicating the CD24/P-selectin axis in cancer stemness maintenance." (PMID 30467381, 2019). "Recently, CD24 was described as a major “don't eat-me” signal exploited by tumor cells to evade the immune response." (PMID 31998312, 2019). "CD24 is not only found in tumor cells, but is also expressed in hematologic cells (monocytes, granulocytes, B/T lymphocytes) at variable levels." (PMID 30717444, 2019). "Subsequently, colony formation and tumor sphere assays revealed significant decreases in CFUs for CD24, CD133, EpCAM, and E-cadherin shRNA knockdown clones compared to sheGFP controls (P < 0.05)." (PMID 30467381, 2019).
tumor (continued). "CD24 is overexpressed by a variety of tumor cells, inhibiting phagocytosis by neighboring tumor-associated macrophages, which express high levels of Siglec-10." (PMID 31998312, 2019). "As a result, several tumor cell lines have been shown to be oncogenic addicted to CD24 overexpression as their growth and metastasis are diminished upon inactivation of CD24 expression." (PMID 31244889, 2019). "When all tumors from one mouse were combined, Cd24−/− mice bore a 5.1-fold larger tumor volume than WT mice (844.8 ± 219.3 vs 166.4 ± 64.4, p = 0.0002)." (PMID 29423273, 2018). "The CD44+/CD24- tumor cell fraction is increased in breast cancer patients upon administration of neoadjuvant chemotherapy." (PMID 29455658, 2018). "This, in turn, changed the percentage of tumor cells with certain CD44/CD24 expression patterns and changed the percentage of tumor-infiltrating immune cells." (PMID 29925435, 2018). "Seven and eight tumours were developed in a total of ten flanks of five mice injected with spheroid CD24-Ctrl BFTC 909 and CD24-Ctrl BFTC 905 cells, respectively, within a 70-day follow-up period after cell injection." (PMID 30327565, 2018). "We cultured these tumor cells and found that most (> 90%) of the cells maintained their CD24+CD29high feature and less than 2% of the cells were CD24+CD29low, whereas, as a control, about half of the p18−/− tumor cells were CD24+CD29low." (PMID 29996906, 2018). "Next, we assessed the ratio of CD44+CD24-/low cells, the subpopulation that have been demonstrated to adopt stem-like phenotypes and tumor-initiating potential." (PMID 30555330, 2018). "In our study, we confirmed that CD24 is highly expressed in HCC tumor tissues compared to the adjacent tissues." (PMID 29844385, 2018). "RTK signaling in tumor and stromal cells plays a critical role in the regulation of both CD24- and CD44+ and ALDH+ve CSC phenotypes." (PMID 29455658, 2018). "Given the cancer-specific elevation of CD24 expression in primary tumours, we next assessed the potential for non-invasive cancer detection using a total of 48 urine samples (24 UCB and 24 control subjects) as a training cohort." (PMID 30327565, 2018). "Representative flow cytometry plots for recovered tumor cells are shown in (D), where the R22 gate denotes EPCAMHigh/CD44High cells, and CD24 +cells are donated in red." (PMID 30074477, 2018). "The cell surface factor CD24 has been shown to be an effector of HIF-1α driven primary tumor growth and metastasis." (PMID 29552303, 2018). "The concordance rate between primary tumours and the matched urine samples (analytical sensitivity) was 77.8% (7/9) for CD24, 70.0% (7/10) for CD49f, and 64.3% (9/14) for NANOG." (PMID 30327565, 2018). "As an important feature of CSCs is efficient in vivo tumorigenesis at a limiting-dilution xenograft, we performed the tumour formation assays with serial dilutions of spheroid CD24-sh cells and CD24-Ctrl cells." (PMID 30327565, 2018). "Immunofluorescence assay showed that ALDH1+ BCSCs and CD44+CD24− BCSCs are localized in different regions within the tumour tissue." (PMID 29780673, 2018). "In contrast, the spheroid CD24-sh cells showed decreased tumour initiation frequency (development of three and four tumours per ten flanks of mice for CD24-sh BFTC 909 and CD24-sh BFTC 905 cells, respectively)." (PMID 30327565, 2018). "The intensity of CD24 staining was between +2 and +3 for all the tumor samples and was present only in the well-differentiated areas of the tumors." (PMID 30550540, 2018). "The increase in liver weight is attributable to increased tumor size, as the diameters of the largest tumors in Cd24−/− mice (7.7 ± 0.9) were nearly twice as those in the WT littermates (4.4 ± 0.7) (p = 0.0057)." (PMID 29423273, 2018). "In mammary and tumor cells ERα expression is restricted to the CD24+CD29low luminal population while the CD24+CD29high population is ERα negative while also enriched with basal and stem cells." (PMID 29996906, 2018).
tumor (continued). "The difference in the CD24+ population is further increased between the 2nd xenografts derived from the 1st sorted EGFP+ tumor cells and those derived from 1st sorted EGFP− cells." (PMID 29510720, 2018). "As CSCs are resistant to conventional chemotherapies that efficiently eliminate bulk tumour cells, the viability of spheroid CD24-sh cells was analysed by treating with cisplatin (CDDP), an important chemotherapeutic agent for the treatment of UCB." (PMID 30327565, 2018). "Comparable with our in vitro assays data, the spheroid CD24-sh cells had significantly reduced tumour growth compared with the spheroid CD24-Ctrl cells." (PMID 30327565, 2018). "After treatment with GCSF-neutralizing antibody, we observed that pre-DCs and CD24+ cDC1s in the BM and pre-DCs in the blood were restored to levels in tumor-free mice." (PMID 29593283, 2018). "Consistent with previous reports, CD24 showed significantly higher expression in primary tumours compared with the corresponding adjacent normal tissues." (PMID 30327565, 2018). "Attenuation of CD24 activity by anti-CD24 monoclonal antibodies can reduce tumor volume in vivo and inhibit cancerous cell growth in vitro." (PMID 29390019, 2018). "Patients with enhanced AR or let-7a expression predicted a better prognosis, while the tumor cells with CD44+/CD24-/low phenotype predicted a worse prognosis index." (PMID 29423076, 2018). "The spheroid CD24-Ctrl cells were sufficient for tumour development by injecting as few as 100 cells into NSG mice." (PMID 30327565, 2018). "IHC analysis in tumor xenografts also showed decreased expression of the CSC markers CD24 and ALDH1 in afatinib alone and in pre-treated tumors." (PMID 28423495, 2017). "CD24 expression was observed in a minority of hepatocarcinoma cells in primary tumor specimens (ranging from 0% to 16%), while its expression was absent in nontumoral hepatic tissue." (PMID 28930164, 2017). "The ability of a single cell to move from the primary tumor to metastatic site is facilitated through the transition from an epithelial phenotype (CD44+/CD24+) to a mesenchymal phenotype (CD44+/CD24-)." (PMID 28609459, 2017). "Under the condition of the uniform inoculum size, the tumor incidence in vivo induced by CD133+/CD24+ cells was higher than that in the parental cells." (PMID 28279221, 2017). "Like CD44, in cancer, CD24 is involved in cell-cell and cell-matrix junction and in cell migration, and is a significant marker for tumor prognosis as well as diagnosis." (PMID 28445439, 2017). "In these patients, CD44+CD24- cells were present mainly in solid (96.4% of cases), alveolar (91.6%), trabecular (75.0%), tubular (57.9%), and discrete groups of tumor cells (33.3%)." (PMID 28977854, 2017). "CD24+ cells isolated from primary tumors displayed properties of cancer stem cells (as few as 500 of CD24+ cells are sufficient to induce tumor formation in immunodeficient mice)." (PMID 28930164, 2017). "CD24 acts as a ligand for P-selectin and appears to contribute to the acceleration of tumor growth and metastases." (PMID 28611669, 2017). "As for the CD44+/CD24-/low cell fractions, one showed tumor-specific CNAs, while the other two were balanced." (PMID 28423035, 2017). "Attention also has shifted to CD24 due to its important role in the development of cancer metastases and as a marker of malignancy in several tumor types." (PMID 28609459, 2017). "It was revealed that in vitro tumor cell-derived exosomes contained CD24 and that it was also present in exosomes obtained from malignant ascites." (PMID 29262670, 2017). "Although CD24 was excluded from the analysis since it was expressed by most tumor cells in our ascitic effusion samples, CD44+CD117+ cells significantly overexpressed NANOG, SOX2 and OCT4, compared with the negative counterpart CD44+CD117−." (PMID 28726781, 2017). "Another TNBC line MDA-MB-231-with knockdown of CD24 also showed improved tumor response to docetaxel as predicted by the in vitro data." (PMID 28418843, 2017).
tumor (continued). "In breast and rat mammary carcinomas, CD24 is known as a marker for metastasis due to its binding to P-selectin which facilitated the passage of tumour cells in the bloodstream during metastasis." (PMID 28959019, 2017). "Accordingly, tumor cells in OC peritoneal effusions were reported to express higher levels of CD24 than solid tumors, which was proposed as a sign of enrichment in CSC traits." (PMID 28320418, 2017). "In fact, a subpopulation of cancer cells enriched as tumor-initiating cells with the antigenic phenotype CD44+/CD24- has been increasingly found in metastatic breast cancer, in comparison to the majority of carcinoma cells, which are CD44-/CD24+ phenotype." (PMID 28609459, 2017). "The first line of evidence for the existence of BCSCs demonstrated that a celluar population with CD44+CD24- phenotype displayed the capacity to initiate new tumours in NOD/SCID Mice." (PMID 29221160, 2017). "On the other hand, tumors of HCC1806 cells with CD24 knockdown demonstrated significant tumor reduction after docetaxel treatment as compared to controls." (PMID 28418843, 2017). "In our experiment, control tumours displayed a significantly stronger expression CD24+/CD44+ cells than tumours with down-regulation of Six1." (PMID 28388884, 2017). "CD8+ tumor cells are CD24+, icTCRβ+, and mTCRβ–, thus indicating that they derive from the abnormal expansion of immature single CD8-positive (ISP) cells." (PMID 29136506, 2017). "CD49f (integrin subunit α6) is a marker for breast cancer progenitor cells, whereas CD24 is highly expressed on both CSCs and tumor transit amplifying cells." (PMID 28418883, 2017). "High CD44/CD24 ratio was mainly in charge of self-renewal, proliferation, and tumor growth, while ALDH1+ represented a stronger capability for invasion and metastasis." (PMID 29062075, 2017). "A mesenchymal, migratory CD44+/CD24- CSC subpopulation exists at the tumor edge, while an epithelial, proliferative ALDH+ CSC subpopulation resides within the tumor core." (PMID 29348905, 2017). "In general, epithelial cell lines and tumors were associated with cancer stem cell markers (CD24, ALDH1A1, and PROM1), markers of tumor aggressiveness (MYCL1 and ASCL1), and markers of apoptosis (BCL2 and BCL2L11)." (PMID 28212573, 2017). "Four out of five control tumours were CD44+/CD24+ whereas all Six1-downregulated tumours lost that phenotype and were CD44−/CD24+." (PMID 28388884, 2017). "CD24 (red) exhibited a strong or moderate staining on both membrane and cytoplasm of tumor cells, predominantly present on the apical membrane of malignant ducts in PDACs." (PMID 28369074, 2017). "The fact that more than 90% of EVs, either derived from ascites or from conditioned medium of LBC cells, express CD8 and CD24 suggests the tumor origin of the EVs A." (PMID 28360912, 2017). "We analyzed the clones’ CD44+/CD24- markers, in vitro sphere formation, and tumor formation in xenograft mice." (PMID 29137367, 2017). "The highest proportion of CD24+/CD44+/EpCAM+/CD133+ cells was detected in the cell line derived from the tumor of a patient with the shortest survival." (PMID 27414409, 2016). "Overall, there is strong evidence for a pivotal role of CD24 in tumor cell migration and cell proliferation." (PMID 27203385, 2016). "Cell surface proteins such as CD44 and CD24 are used to distinguish cancer stem cells (CSCs) from the bulk-tumor population." (PMID 27521216, 2016). "Based on these findings, CD24 cell surface marker in CSC phenotype fluctuates with tumor environment and cell expansion, suggesting that the role of CD24 in OCSC remains plastic and inconclusive, and further investigation is needed to elucidate its role." (PMID 27304054, 2016). "NDRG2 inhibits CD24 expression and further suppresses tumor adhesion, migration and invasion in HCC." (PMID 26506239, 2016).